CD44 (CD44 molecule (IN blood group))
Diseases named in the same sentence as CD44 in open-access papers (continued):
Sharing a sentence is not in itself a finding about the gene and the disease.
cancer (continued). "Asbestos can induce inflammatory changes, including increase in MMP7, CXCR5, CXCL13, and CD44, and this chronic inflammation can lead to chronic diseases, such as cancer." (PMID 35036082, 2022). "Among these 16 proteins, proteins reflecting the cellular origin (HLA-DR, HLA-DP, HLA-DQ, CD31, CD41b, CD42a), activation markers (CD62p), EV markers (CD9, CD63, CD81), and cancer related markers (CD44 CD29, CD105, CD146) were found." (PMID 35012489, 2022). "Our data showed that GSK J4 treatment significantly reduces the transcript levels of SOX2, SOX9, and CD44 genes in detached cancer cells compared to the untreated control." (PMID 35186918, 2022). "For antioxidant metabolism, overexpression of the cancer stem cell marker CD44 enhances the stability of SLC7A11, a key regulator of lipid peroxidation, and inhibits ferroptosis in cancer cells." (PMID 34784264, 2022). "Since CD44 is also expressed in immune cells, we investigated the proportion of cells expressing both the cancer biomarker CA125 and the membrane fluidity-related protein CD44 (n=6) in HGSOC." (PMID 36789687, 2022). "Conversely, the mesenchymal markers fibronectin and vimentin, the cancer stem cell marker CD44, the EMT‐TFs Zeb1 and Snail were all strongly increased." (PMID 35348275, 2022). "We also characterized the MIAPaCa2 cancer stem cells for the expression of the typical surface stem cell markers, namely CD44, CD133, and EpCAM." (PMID 35634239, 2022). "CD44 is a stem cell biomarker enhancing cancer cell invasiveness, chemoresistance and EMT‐properties." (PMID 34951143, 2022). "Previous studies have shown that LWHA can efficiently target CD44 receptor overexpressed on cancer cells and can be internalized via CD44-mediated endocytosis." (PMID 35303862, 2022). "TAT, derived from the virus HIV, is a cell-penetrating peptide able to favor cell uptake; HA allows the targeting to CD44, overexpressed in many cancer cells." (PMID 36297407, 2022). "The molecular mechanistic studies revealed that CD44 plays a pivotal role in controlling FOXA2 localization to promote cancer metastasis via the AKT signaling pathway." (PMID 36289750, 2022). "CD44 is a cell surface glycoprotein, which is expressed on normal cells, and overexpressed on cancer cells." (PMID 35628345, 2022). "More importantly, a positive correlation between CD44 and CD206 expression was observed, implying an intimate association of high frequency between CD44high cancer cells and CD206+ macrophages at the invasive edges." (PMID 35680853, 2022). "The Wnt/β-catenin signaling pathway regulates the expression of the canonical cancer stem cell marker CD44 directly or through the intermediate c-Myc." (PMID 35884507, 2022). "To address this possibility, we first detected the function of COL11A1 in the expression of cancer stem cell (CSC)-associated markers (cluster of differentiation (CD)-24 and CD44) in PDAC using Western blotting." (PMID 35327583, 2022). "High expression of CD44 leads to cancer cell proliferation, motility, and survival and promotes cancer metastasis." (PMID 36551786, 2022). "Our data suggest that the rapid and sustained upregulation of KDM6B following matrix detachment is necessary for SOX2 and CD44-mediated stemness to enhance anchorage-independent survival of various cancer patients’ cells." (PMID 35186918, 2022). "Cluster of differentiation 44 (CD44) is a transmembrane glycoprotein and functions in various cellular processes, such as angiogenesis, bone metastasis, cell migration, and cancer invasiveness." (PMID 35733341, 2022). "Then enhanced ASGR2 induced typical cancer hallmarks such as proliferation, N-cadherin, CD44, PD-L1 for both in vitro and in vivo." (PMID 35547772, 2022). "This establishes CD44 as a biomarker in cancer diagnosis, particularly for breast, colorectal, head and neck, pancreas, bowel and prostate cancers." (PMID 35762636, 2022).
cancer (continued). "CD44, a transmembrane glycoprotein, is considered one of the dominant markers on the surface of cancer stem cells in TNBC." (PMID 35845934, 2022). "The interaction of CD44 with certain extracellular matrix ligands promotes the process of cell migration and invasion in cancer metastasis." (PMID 34939255, 2022). "In a meta-analysis study, it has been reported that CD44 is associated with EMT and the cancer stem cell gene profile." (PMID 36289750, 2022). "In the HNSCC context, cancer stem cells are responsible for treatment failure in which CD44 has been reported to represent a candidate of resistance marker." (PMID 35011716, 2022). "Preclinical and clinical trials of CD44 monoclonal antibodies have also been performed to evaluate the pharmacokinetics, efficacy, and drug-related toxicity in cancer." (PMID 35493471, 2022). "CD44 expression is up–regulated in subpopulations of cancer cells and also recognized as a molecular marker for CSCs." (PMID 36059616, 2022). "In the following section, we focus on the roles of the interaction of the VEGF/VEGFR2 axis and CD44 with lipid rafts in cancer metastasis." (PMID 34939255, 2022). "The decreased expressions of β-catenin-dependent cancer stem cell markers (CD44, EpCAM, Notch 1, and Oct4) advocated for the inhibition of metastatic progression." (PMID 36362950, 2022). "As the key regulator of CD44, BRG1 is known to positively regulate the expression of CD44 in several cancer cell lines." (PMID 35590122, 2022). "By interacting with its receptor CD44, hyaluronan regulates several aspects of cancer stem cell biology." (PMID 36497283, 2022). "Overall, we found that matrix detachment modulates the epigenome during anoikis, inducing KDM6A/B that positively regulates the expression of SOX2, CD44, and HIF1α to regulate survival and stemness of cancer cells." (PMID 35186918, 2022). "To increase the uptake and ROS generation in cancer cells, we modify the surface of ZrO2-acac NPs with hyaluronic acid (HA), which recognizes and binds to the surface antigen CD44 overexpressed on OS cells." (PMID 36615964, 2022). "Compared to cancer cells co‐cultured with HSCs, HSCs‐PD‐1 co‐incubation displayed a dramatic increase in CD44 signaling." (PMID 35948516, 2022). "Due to AKT1/luciferase gene transposition, the HCC clones exhibited bioluminescent reporter gene activity, as well as higher levels of MHC class I protein (H-2Kb) and the cancer stem cell (CSC) marker CD44 compared to Hepa1-6 cells." (PMID 35721518, 2022). "show that receptor-meditated endocytosis by hyaluronic acid for targeting of CD44-overexpressing cancer cells has promising therapeutic prospects." (PMID 35024436, 2022). "The capacity of cancer stem cells to metastasize, propagate and resist chemotherapeutic treatments has made CD44 expression on tumor cells a biomarker of cancer stem cells." (PMID 36091772, 2022). "In 2019, Huiping Liu uncovered that aggregated cancer cells highly expressed CD44 and the results showed enhanced tumorigenesis and polyclonal metastasis of CTC clusters." (PMID 36059616, 2022). "CD44 is widely used as a marker for the identification of CSCs in various cancers, including that of the brain." (PMID 36231019, 2022). "CD44v6, an adhesion molecule from the CD44 transmembrane glycoprotein family, has been particularly involved during evolution of several cancers and incorporates some reported possible stem cell properties." (PMID 35625534, 2022). "Various types of cancer, including lung cancer, express CD44, which has been shown to be a poor prognostic factor." (PMID 35884975, 2022). "All three of these cancer types are digestive tract cancers, suggesting digestive cancer tissues from patients tend to express both CD44 and GABRPmolecules." (PMID 35846884, 2022). "We showed that cancer stemmess (CD44+ in this study) 18, 19, 52, 53 increased by PS exposure through ASGR2." (PMID 35547772, 2022).
cancer (continued). "Some of the first markers identified in cancer stem cells were CD44, CD24, and later an enzyme aldehyde dehydrogenase (ALDH or ALDH1); these markers were studied with fluorescence-activated cell sorting or immune selection methodologies." (PMID 36120232, 2022). "For the first time, we demonstrated polyploid giant and/or multinucleated cancer-cell (PGCC/MGCC) fractions mainly featuring the progressively augmenting Ki67low phenotype in CD44+ and CD133+ A549 cells at 24–48 h after IR." (PMID 35563313, 2022). "In this study, we aimed to investigate the engagement of CD44, a cancer stemness marker functioning in the control of cell growth and motility, in OSCC malignancy under the influence of MRE11." (PMID 35629265, 2022). "On the other hand, in metastasis, the elevated levels of soluble CD44 in the serum of cancer patients are observed in various human cancers, and can be considered a marker metastasis CD44 is present outside LRs." (PMID 35207103, 2022). "For targeting, the DOX-NGs were coated with platelet membrane since platelets express p-selectin, a molecule that binds to CD44, a receptor often up-regulated on cancer cells." (PMID 36291908, 2022). "CD44-positive cells have been suggested to be involved in the epithelial-mesenchymal transition (EMT), a genetic process associated with cancer invasion and metastasis." (PMID 35200757, 2022). "Stimulation by growth factors and cytokines efficiently activate CD44 cleavage in various types of cancers, such as transforming growth factor β (TGFβ) in lung cancer and platelet-derived growth factor (PDGF)-BB in breast cancer." (PMID 35954411, 2022). "This highlights the existence of a poorly developed field of research that needs to be completed to define in detail the role that CD44 plays in these types of cancer." (PMID 35785191, 2022). "Currently, the potential of hyaluronic nanoparticles in imaging techniques is being studied, mostly because of its ability to bind to tissues overexpressing CD44, as is the case of some cancer tumors." (PMID 35456670, 2022). "We recently showed that CD44+/CD54+ GCSCs isolated from cancer tissues can survive and expand after treatment with 5-FU and cisplatin." (PMID 36176765, 2022). "Hyaluronic acids from mesothelial cells are specific ligands of the transmembrane glycoprotein CD44 from PFCCs, and CD44 isoforms enhance local growth and metastasis of cancer cells." (PMID 35054150, 2022). "CD44 is a cell surface adhesion receptor that is highly expressed in many cancers and regulates metastasis via the recruitment of CD44 to the cell surface." (PMID 36499093, 2022). "The nanocarrier was tested in cancer cells expressing CD44, effectively killing cancer cells by inducing apoptosis." (PMID 36612002, 2022). "CD44 has been previously shown to be a prominent marker for cancer stem cells and HA-CD44 interactions mediate self-renewal and maintenance of these cells." (PMID 35907870, 2022). "The CD44 antigen is a potent cancer biomarker that is a multifunctional transmembrane glycoprotein having malignant cellular features such as cell adhesion, activation, migration, and differentiation." (PMID 36354475, 2022). "We summarize that CD44 promotes cancer cell migration through the cytosolic localization of FOXA2 mediated by the AKT signaling pathway." (PMID 36289750, 2022). "As a well-recognized CSC marker in PC and other cancers, CD44+ PC cells displayed significantly enhanced tumorigenicity and metastasis compared with CD44- cells, and small numbers of CD44+/CD24- initiated tumors in a xenograft model." (PMID 36358865, 2022). "More importantly, it was demonstrated that ZnO NPs effectively down regulated CD44, a key cancer stem cell marker leading to successful killing of the cancer cells." (PMID 36552345, 2022). "CD44 is an important marker of CSC’s in carcinomas, and it plays a role in the mediation of resistance to drug therapy, including anti-EGFR inhibitors." (PMID 35011716, 2022).
cancer (continued). "Due to pleiotropic roles in carcinoma, CD44 can be considered a new molecular target for therapeutic intervention." (PMID 35845934, 2022). "CD44 is an endocytic HA receptor that is overexpressed in several types of carcinomas and involved in many physiological and pathological pathways." (PMID 35056160, 2022). "The expression of CD44 promotes EMT by activating the CD44/EGFR/PI3K-Akt and CD44/NF-κB signaling pathways in carcinoma." (PMID 36499654, 2022). "The internalization mechanism was CD44 receptor-mediated endocytosis and the NPs were more cytotoxic towards HCT-116 cells (CD44-overexpressing cancer cells) than towards NIH-3T3 cells (CD44-negative cancer cells) due to increased cellular uptake." (PMID 33981532, 2021). "The expression level of CD44 on the cell surface is closely related to the metastatic potential of cancer cells." (PMID 34360949, 2021). "The expression level of CD44 is positively correlated with the wild-type EGFR level in cancer tissues." (PMID 33981532, 2021). "To date, the known representative markers of cancer stem cells (CSCs) comprise CD44, CD24, CD105, and CD133, and additional surface traits are typically tissue-specific." (PMID 34062950, 2021). "The average frequency of CD44-/CD24- cancer cells in all samples was 19.7% with a median value of 19.5%." (PMID 34318746, 2021). "Usually, HA-modified liposomes are developed for cancer treatments, given the high expression rate of CD44 on cancer cells." (PMID 34299359, 2021). "HGF is reported to enhance cancer stemness by potentiating the frequency of CD44+, CD47+, and CD90+ HCC CSC and spheroid formation, stemness and EMT gene expressions." (PMID 34760886, 2021). "Consistent with its potential role in cancer cell dissemination, CD44 was upregulated in CTCs in three of four models, while CD24 was downregulated in two of four models." (PMID 34206049, 2021). "Since EGFR pro-oncogenic roles have been widely implicated in many cancer types and several drugs have been developed and clinically approved to target EGFR, we focused our analysis on CD44." (PMID 34301218, 2021). "Numerous studies have reported the presence of stem-like subpopulations in NSCLC, using common cancer stem cell (CSC) markers such as CD44, CD133 and ALDH1." (PMID 34685477, 2021). "Multiple markers have been identified that are present in normal intestinal and cancer stem cells, including, but not limited to CD44, CD24, CD166, CD133, telomerase (TERT), doublecortin calmodulin-like kinase 1 (DCLK1), and LGR5." (PMID 34206989, 2021). "For example, CD44 plays a key role in the acquisition and maintenance of cancer stemness via binding to hyaluronan." (PMID 33535613, 2021). "Self‐assembled liposome‐porphyrin (Lip‐p‐OH) was modified with an HA derivative to target CD44‐overexpressed cancer cells, such as MDA‐MB‐231 cells." (PMID 34085415, 2021). "The IHC results revealed the correlation between TDO2 expression and cancer stem cell markers (CD44 and ALDH1) in BC." (PMID 34101386, 2021). "For example, while HA has been shown to target specific cancers through CD44 interactions with great success, CD44 is expressed in most cell types making this mechanism inherently non-targeted." (PMID 33737507, 2021). "Our study results showed a trend (p = 0.079) toward lower fruit intake in cancer cases compared to controls; however, CD44 levels trended toward higher levels in the cancer cases who had higher fruit intake." (PMID 33530399, 2021). "In vivo studies using zebrafish cancer models showed that the glycoprotein CD44 and the integrins αvβ3 and α5β1 are required for weak (CD44 and αvβ3) and strong (α5β1) interactions between CTCs and endothelial cells." (PMID 34571870, 2021).
cancer (continued). "Since TNBC population express increased number of cancer stem cells with CD44+/CD24−, we evaluated the levels of these markers in the TNBC population following SF treatment." (PMID 34873206, 2021). "ENAH and CD44 are amongst the most studied splicing events impacting cancer and are well-known biomarkers of poor prognosis." (PMID 33845831, 2021). "Increasing evidence suggests that some CD44 isoforms are promising prognostic biomarkers and therapeutic targets for many cancers." (PMID 34944493, 2021). "Specific interactions between CD44 and HA are of major importance for the maintenance of the proper (stem cell) niche properties under physiological conditions and the biology of cancer stem cells under pathological circumstances." (PMID 34065048, 2021). "Results show that pharmacological doses of both Ndn and Bdn, already after 7 days of poPSCs culture, caused a significant increase of selected, stemness-related markers of cancer cells: CD44 and CD133." (PMID 34769230, 2021). "In this study, we found that the expression of CD105 and the ratio of CD44+ CD90+ CD133+ cells were upregulated by EVs derived from cancer cells." (PMID 34746322, 2021). "It has been reported that CD44 plays a role in cell-cell interactions, cell adhesion, migration and acts as a metastasis-promoting molecule in many types of cancer." (PMID 33627162, 2021). "The expressions of ALDH1, c-MET and CD44 were enhanced in cancer cell clusters attached to the metastases compared with those in sherbet-like aggregates in Amatuximab mice." (PMID 33637083, 2021). "In contrast, the expression of Ang 1 in cancer cells through adenoviral vector-mediated transfection has been reported to induce cancer metastasis via overexpression of β1 integrin and CD44." (PMID 34588926, 2021). "HA is a biocompatible, biodegradable, and nonimmunogenic biopolymer capable of actively targeting Cluster of differentiation-44 (CD44) on cell surface receptors overexpressed in many cancer cells." (PMID 33513992, 2021). "The down-regulation of the cancer stem cell marker CD44 expression was further confirmed in Panc-1 cells." (PMID 34349642, 2021). "In the present study, we also showed a correlation between the expression TDO2 and CD44, a cancer stem cell marker." (PMID 34174844, 2021). "High expression of CD44 promotes SRC activation to induce cancer stemness and EMT features of GBM cells." (PMID 34681583, 2021). "With all methods, we observed an extraordinarily strong positive correlation between TMEM doorway density and the proportion of cancer cells expressing stem cell markers (CD44+/24−, CD133, and ALDH1)." (PMID 34911937, 2021). "CD44 is a membrane-bound glycoprotein that plays an important role in malignant tumor-related activities." (PMID 35082668, 2021). "The curcumin-CD44 coupling stimulates apoptosis in colorectal stem cells via preventing influx of glutamine into cancer cells and reducing its intracellular accumulation." (PMID 34769099, 2021). "Several studies have indicated that CD44 cooperates with integrins to regulate cancer cell adhesion and mobility." (PMID 34944101, 2021). "Cluster of differentiation 44 (CD44) is a multifunctional transmembrane glycoprotein expressed in many types of cancer." (PMID 34709167, 2021). "CD44 AS-mediated positive feedback loop promotes cancer migration and invasion processes and interacts with extracellular matrix ligands." (PMID 35004299, 2021). "Univariate and multivariate analyses indicated that high frequency of CD44-/CD24- cancer cells or CSCs, positive lymph node metastasis, higher N stage, and TNBC were independent risk factors for poor DFS." (PMID 34318746, 2021). "To explore this point further, we tested the effects of Abs against two cell surface molecules that play central and interactive roles in cancer cell migration and adhesion, CD44 and RHAMM." (PMID 34338608, 2021).